PTPN22 (protein tyrosine phosphatase non-receptor type 22)
Diseases named in the same sentence as PTPN22 in open-access papers (continued):
Sharing a sentence is not in itself a finding about the gene and the disease.
Autoimmunity (continued). "Taking into consideration the contribution of autoimmunity to LTx outcome, we hypothesized that polymorphisms in the PTPN22 gene could be associated with BOS incidence." (PMID 30705675, 2018). "Besides investigations on associations in autoimmunity and functional implications on T cell receptor signaling, PTPN22 SNPs are also studied in the field of transplantation." (PMID 30705675, 2018). "The PTPN22 gene is considered to be one of the most important autoimmunity risk genes." (PMID 30705675, 2018). "Taking into consideration the results obtained in liver transplantation, the associations of PTPN22 with autoimmunity and the observed features of autoimmunity in LTx, we hypothesized that SNPs in the PTPN22 gene could be associated to outcomes after LTx." (PMID 30705675, 2018). "Translating these observations to the field of LTx suggests that a decreased suppression of Th-1 immune responses in patients genotyped with the risk variant of PTPN22 could contribute to autoimmunity and the pathogenesis of BOS development." (PMID 30705675, 2018). "The human variant of PTPN22 R619W is strongly associated with autoimmunity." (PMID 28747914, 2017). "PTPN22 R619W knock-in mice, which are analogous to the human R620W variant and show a similar, albeit milder phenotype to that of the Ptpn22−/− mouse, were found to develop multiple features of autoimmunity on a susceptible mixed B6/129 background." (PMID 27288531, 2016). "Possible reasons for the association between systemic ANCA associated vasculitis and RA may be the common genetic predispositions to autoimmunity which involve the HLA region or genes such as PTPN22, reported in series of both RA and AAV." (PMID 25664229, 2015). "Two well-known CSK (CSK rs34933034 and CSK rs1378942) and two functional PTPN22 (PTPN22 rs2476601 (R620W) and PTPN22 rs33996649 (R263Q)) polymorphisms, previously associated with autoimmunity, were genotyped with TaqMan single nucleotide polymorphism (SNP) genotyping assays." (PMID 26458874, 2015). "The variant PTPN22 allele confers to carriers a roughly two-fold increased risk of autoimmunity." (PMID 24498279, 2014). "Individuals carrying the variant allele of PTPN22 (T allele encoding W620) may have changes in the threshold for thymic selection and be prone to autoimmunity." (PMID 25119822, 2014). "The authors hypothesized that the high-risk INS genotype is likely involved in the induction and early phases of beta cell autoimmunity and the high-risk PTPN22 in the later stages." (PMID 23360422, 2013). "In addition, the R263Q (G788A; rs33996649) polymorphism located within PTPN22 exon 10 has also been associated with autoimmunity." (PMID 23559857, 2013). "Interestingly, the PTPN22 gene has emerged as an important genetic risk factor for human autoimmunity by multiple mechanisms, including altered thymic selection, reduced T-helper activity, and decreased number or function of regulatory T cells." (PMID 23559857, 2013). "Consequently, the capacity of PTPN22 to downregulate T cell responses may be reduced, thereby increasing susceptibility to autoimmunity." (PMID 33746952, 2021). "Further study of the interaction between PSTPIP1 and PTPN22 might help understanding the spatial regulation of PTPN22 in T cells, which is crucial to understand how the R620W polymorphism drives autoimmunity (further discussed in section “Tyr Phosphatases in T Cells”)." (PMID 33425916, 2020). "Therefore, a failure to maintain cDC homeostasis, as conferred by the PTPN22 risk allele, may be a factor altering the downstream immune responses that ultimately lead to autoimmunity." (PMID 32194571, 2020). "Notably, the autoimmunity-associated PTPN22 variant was more effective in NLRP3 dephosphorylation." (PMID 32751912, 2020).
Autoimmunity (continued). "Whereas, this study indicates that a normalized BCR signal could restore immune tolerance, the strong role of CD40 activation in PTPN22 risk gene carriers is also consistent with the idea that this pathway is critical for censoring the overly active immune system in autoimmunity." (PMID 31616406, 2019). "Factors that may influence the strength of the TCR signal between different disease-affected individuals include autoimmunity-associated genetic variations (for example, PTPN22, a protein tyrosine phosphatase that regulates TCR signal transduction) and the antigenic trigger(s)." (PMID 26276872, 2015). "Moreover, we investigated the role of PTPN22 C1858T polymorphism in autoimmunity." (PMID 23936838, 2013). "Therefore, the study of PTPN22 C1858T polymorphism is of enormous clinical and therapeutic interest, as Lyp could be the target of intervention against triggered autoimmunity." (PMID 23936838, 2013). "The protein tyrosine phosphatase non‐receptor type 22 (PTPN22) gene on chromosome 1 was also shown to contribute to polyglandular autoimmunity." (PMID 41317333, 2026). "A genetic variant in the PTPN22 gene (R620W, rs2476601), which encodes a protein that belongs to the PTP family, contributes to the risk of autoimmunity by allowing increased T-cell receptor (TCR) signalling and activation in autoreactive T cells." (PMID 41244914, 2025). "The enrichment and burden tests performed in comparison with a control group underline that the products of expression by the variants involved belong to the autoimmunity and immune regulation pathways (i.e., SPINK5, PTPN22 and PSMB9)." (PMID 40725177, 2025). "The rs2476601/PTPN22(G/A) SNP is a functional missense variant that dampens TCR/BCR signaling, thusimpacting autoimmunity by increasing the number of autoreactive T and B cells thatevade central tolerance." (PMID 40261241, 2025). "PTPN22*W polymorphism influences TCR signaling and augments the TCR-initiated response to promote autoimmunity." (PMID 36013501, 2022). "PTPN22 is considered one of the strongest genetic risks for the development of autoimmunity, with the exception of the HLA region." (PMID 35967336, 2022). "Recent data confirm that carriers of the risk alleles PTPN22 1858T and CTLA4 CT60 are more prone to develop several autoimmune conditions." (PMID 33966174, 2021). "In conclusion, our study shows that the PTPN22 rs2476601 and CTLA4 rs3087243 autoimmunity risk variants are more frequent in patients with ITO ME/CFS." (PMID 32328064, 2020). "With aging, PTPN22 mutant mice develop many hallmarks of autoimmunity including increased effector T cells, activated B cells and higher immunoglobulin and autoantibody titres." (PMID 32194571, 2020). "Analysis of 305 ME/CFS patients and 201 healthy controls showed significant associations of the PTPN22 rs2476601 and CTLA4 rs3087243 autoimmunity-risk alleles with ME/CFS." (PMID 32328064, 2020). "We found a strong association of the autoimmunity risk alleles in CTLA4 rs3087243-G and PTPN22 rs2476601-A with ITO ME/CFS." (PMID 32328064, 2020). "The presence of autoimmunity associated PTPN22 variant in mice (PTPN22-619W) resulted in dephosphorylation and activation of NLRP3, while loss of PTPN22 resulted in decreased NLRP3 mediated IL-1β secretion." (PMID 30915320, 2019). "While there have been a number of studies addressing the role of PTPN22 in different models of autoimmunity, relatively less has been done to address the role of PTPN22 in immunity against pathogens." (PMID 28747914, 2017). "Although a number of PTPN22 targets have been identified in vitro, it is unclear which of these are most relevant to the development of autoimmunity." (PMID 27288531, 2016). "We discuss the implication of these findings for our understanding of the roles of PTPN22 in regulating T cell responses and in autoimmunity." (PMID 25715232, 2015).
Autoimmunity (continued). "Increased positive thymic selection has been reported in Ptpn22 KO mice and in two independently-generated Pep R619W knock-in mouse models, one of which developed spontaneous autoimmunity." (PMID 24498279, 2014). "Identified genes include Ptpn22, previously identified as important in human autoimmunity and a potential therapeutic target, and CD74, a key modulator of B cell maturation and survival." (PMID 19578517, 2008). "The MHC class II, the CTLA4 and the PTPN22 loci have all been proved important in the pathogenesis of autoimmunity globally considered, whereas the insulin gene is a disease-specific T1D predisposition locus." (PMID 17697317, 2007). "Dominant mutations in genes contribute to the overexpression or deletion of proteins, which can result in associated conditions; for example, mutations in protein tyrosine phosphatase non-receptor type 22 (PTPN22) have been linked to autoimmunity." (PMID 40005622, 2025). "Protein tyrosine phosphatase nonreceptor type 22 (PTPN22) is encoded by a major autoimmunity gene and is a known inhibitor of T cell receptor (TCR) signaling and drug target for cancer immunotherapy." (PMID 38777143, 2024). "While these observations suggest an important potential mechanism for how the PTPN22 risk variant promotes autoimmunity, this concept has not been tested in primary human T cells." (PMID 36961507, 2023). "In conclusion, we show that PTPN22 functionally interacts with Ncf1 and is regulated by oxidation via the noncatalytic C129 residue and oxidation-prone PTPN22 leads to increased severity in the development of T-cell-dependent autoimmunity." (PMID 35587260, 2022). "These complex effects also obscure the direct contribution of Csk to PTPN22 R620W autoimmunity." (PMID 35393453, 2022). "Known functions of PTPN22 and their link to autoimmunity have recently been extensively reviewed." (PMID 36359789, 2022). "PTPN22 inhibits TCR signalling, and its missense mutation is also a risk factor for autoimmunity." (PMID 33925355, 2021). "The effect of PTPN22 depends on the respective tissue affected by autoimmunity." (PMID 30871019, 2019). "The higher expression of PTPN22 in CD8+ Teffs in SLE patients prone to flaring could be a mechanism to negatively regulate CD8+ Teff activation to reduce aggressive autoimmunity." (PMID 31781109, 2019). "Thus, PTPN22 appears to act as a critical rheostat on immune cell activation and development of autoimmunity." (PMID 30271775, 2018). "Our results indicate an absence of an association between the selected PTPN22 SNP and autoimmunity, inflammatory, and infectious conditions in TS women." (PMID 30508004, 2018). "Our data reveal that perturbations caused by the autoimmune associated risk variant of Ptpn22 are unlikely to promote autoimmunity via these pathways in DC." (PMID 29040339, 2017). "On a C57BL/6 (B6) background, Ptpn22−/− mice do not show signs of autoimmunity unless the PTPN22 deletion is combined with another susceptibility mutation such as CD45-E163R." (PMID 27288531, 2016). "Similarly, autoimmunity in mouse models has been increased by knocking out Ptpn22 when disease is driven via Abs." (PMID 26438525, 2015). "Because of that, in an attempt to establish if PTPN22/CSK is actually involved in HSP, we analyzed two well-known CSK and two functional PTPN22 polymorphisms, previously associated with autoimmunity, in the largest series of Caucasian patients with this vasculitis ever assessed for genetic studies." (PMID 26458874, 2015). "Humans with autoimmunity often carry a single nucleotide mutation in protein tyrosine phosphatase non-receptor type 22 (PTPN22)." (PMID 25309533, 2014). "Moreover, similar genetic associations, overlapping with other autoimmune conditions, including the HLA-B8, DR3 haplotypes and the R620W variants of PTPN22 have been demonstrated in the case of MG." (PMID 23781375, 2013). "This alternative allele of PTPN22 is considered the highest non-HLA risk allele in autoimmunity." (PMID 38512979, 2024).
Autoimmunity (continued). "Despite its importance in human health, studies have not investigated whether the Ptpn22 autoimmunity associated minor allele impact anti-viral immune responses." (PMID 38512979, 2024). "Interestingly, the combined effect of the PTPN22 s2476601 variant and the HLA-DRB1 shared epitope alleles was further enhanced by smoking, underscoring the importance of gene-environment associations for the development of autoimmunity." (PMID 35979360, 2022). "However, the complete molecular mechanisms explaining the role of PTPN22 in autoimmunity remain unclear, particularly because it is not only expressed in lymphocytes, but in many other immune cells, such as macrophages, monocytes, and dendritic cells." (PMID 36359789, 2022). "Furthermore, all SLE patients carried the normal PTPN22 genetic variant (R620), and not the R620W variant associated with a more severe development of autoimmunity." (PMID 35185888, 2022). "The human leukocyte antigen (HLA), CTLA4, and PTPN22 as T-cell activation regulators are suspected of playing a key role in autoimmunity processes, i.e., the aberrant function of the molecules encoded by them may be responsible for the development of autoimmunity." (PMID 34999914, 2022). "The role of PEP/PTPN22 allotypes in NLRP3 inflammasome may also impact autoimmunity." (PMID 33717184, 2021). "In summary, our findings uncover PTPN22 as a selective regulatory checkpoint required to maintain cDC2 homeostasis, and suggest that early perturbation of DC homeostasis may be a trigger for the onset of autoimmunity." (PMID 32194571, 2020). "PTPN22 interacts with CSK, and this interaction is relevant for PTPN22 function, as shown by the fact that a human PTPN22C1858T variant, encoding an amino acid R620W substitution which impairs its interaction with CSK, is associated with increased risk of autoimmunity." (PMID 33425916, 2020). "In contrast to PTPN22, PD-1 controlled proliferation but had no impact on IFNγ production indicating that negative regulation by PD-1 differs from PTPN22 and that not all co-factors have equal ability to cause autoimmunity." (PMID 32047502, 2020). "Therefore, alterations to PTPN22, as conferred by PTPN22R620W may impact both the quantity and quality of T-cell immune responses, thereby conferring increased risk of autoimmunity." (PMID 30054208, 2018). "Furthermore, PTPN22 binds to C-Src tyrosine kinase (CSK) forming a key complex in autoimmunity." (PMID 28874816, 2017). "Furthermore, we discuss how T cells regulate phosphatase expression, the overlapping and non-redundant functions of PTPN22 and other inhibitory phosphatases in T cell activation and the implications of our results for our understanding of the role of PTPN22 in autoimmunity." (PMID 25715232, 2015). "In conclusion, the lack of association between SNPs in the genetic master switches of autoimmunity, PTPN22 and CTLA-4, suggests that regardless of the strong linkage with HLA-B*27, AAU should be regarded as an autoinflammatory rather than an autoimmune condition." (PMID 19180256, 2009). "PTPN22 Ser449 phosphorylation enables ZAP70-CD45-LCK feedback loop that boosts T cell activation and contributes to autoimmunity." (PMID 40911684, 2025). "We then focused on the distinct roles of PTPN22, SLC11A1, and IRF5 in immune regulation and autoimmunity." (PMID 38675400, 2024). "In SLE patients prone to flaring, increased PTPN22 expression in activated CD8+ T cells is a biomarker of poor prognosis, which again indicates an activated phenotype in flaring autoimmunity." (PMID 31781109, 2019). "The PTPN22 gene is considered to be the most important non-HLA autoimmunity gene, of which the genetic variant rs2476601, 1858 C>T leading to an arginine–tryptophan substitution, is associated with multiple indications of autoimmunity including RA, SLE, and systemic sclerosis." (PMID 30705675, 2018).
Autoimmunity (continued). "Therefore, our data may provide some explanation as to how perturbations to PTPN22 promote autoimmunity later in life, following an alteration of ICAM-1-LFA-1 responsiveness over time, which accumulates to promote the expansion of inflammatory IFNγ responses with aging." (PMID 30054208, 2018). "PTPN22 downregulates this LCK action and thus TCR signaling, and its inhibition can lead to increased risks for autoimmunity." (PMID 28081217, 2017). "A reasonable hypothesis is that the genetic risk for autoimmunity is greater in individuals and families with multiple diagnoses of AIDs, and that for example the SNPs strongly associated with multiple AIDs (such as IL2RA or PTPN22) would be associated with clustering of these diseases." (PMID 29182645, 2017). "Likewise, it is well known that the rate of autoimmunity in general is hugely increased in TS being most pronounced for females with isochromosome Xq, and possibly also affected by the presence of allelic variation of the other genes on other chromosomes, such as PTPN22 gene." (PMID 21406078, 2011). "In this review we describe the roles for PTP nonreceptor type 22 (PTPN22) in the regulation of T lymphocyte signaling and activation in autoimmunity, infection and cancer." (PMID 39039893, 2024). "Protein tyrosine phosphatase, nonreceptor type 22 (PTPN22), is an archetypal non-HLA autoimmunity gene." (PMID 37315092, 2023). "The data do not support an association between SNPs in PTPN22 and CTLA-4, genes regarded as genetic master switches of autoimmunity." (PMID 19180256, 2009). "Mice with homozygous deletion of PTPN22 remain healthy without developing spontaneous autoimmunity but exhibit expanded effector/memory T cell populations, spontaneous GC development, elevated antibodies in the serum, and increased Treg cell numbers with enhanced suppressive and adhesive functions." (PMID 39944077, 2025). "Of note, elevated expression of PTPN22 was highly correlated with this CD8+ T-cell gene expression signature, suggesting that its upregulation could indicate an attempt to regulate Teff hyperactivity during flaring autoimmunity." (PMID 31781109, 2019). "Interestingly neither the PTPN22 R619W nor the full PTPN22 KO mouse show any signs of autoinflammation or spontaneous development of autoimmunity in steady state on the C57Bl/6 background, despite the increased numbers of lymphocytes and their activated phenotype." (PMID 32047502, 2020). "In autoimmune Addison’s disease (AAD), candidate-gene and GWAS data converge on HLA-DR3/DR4 with replicated non-HLA signals (CTLA4, PTPN22, BACH2, SH2B3) and common AIRE effects, extending an “AIRE dosage” concept from rare monogenic APS-1 into common, complex autoimmunity." (PMID 41465179, 2025).